TNF (tumor necrosis factor)
Diseases named in the same sentence as TNF in open-access papers (continued):
Sharing a sentence is not in itself a finding about the gene and the disease.
osteoporosis (continued). "Elderly male patients with osteoporosis had higher expression of RANKL/OPG, TNF-α, IL-6, and lower expression of IFN-γ and IL-10." (PMID 38817601, 2024). "Tumor necrosis factor-α (TNF-α) plays an important role in the initiation and development of osteoporosis." (PMID 38081906, 2023). "There is a balance of bone metabolism between OB and OC, and there is an interaction between TNF-α, RANKL and GSK-3β, which is likely to break this balance and lead to osteoporosis." (PMID 37038178, 2023). "In the study of postmenopausal women with H-type hypertension and osteoporosis, CTX-I was directly related to both TNF-α and IL-6." (PMID 36830779, 2023). "Studies have shown changes in the serum levels of immune factors, including interleukins (ILs) and tumor necrosis factor (TNF), in osteoporosis patients." (PMID 37038178, 2023). "Inflammation mediated osteoporosis presented apparently down-regulated in OPN and OCN levels, higher serum IL-1β, TNF-α, IL-6 levels in ovariectomized rats." (PMID 36387862, 2022). "Osteoporosis is mainly induced by increased levels of inflammatory factors, such as nuclear factor-kappaB ligand (RANKL) and tumor necrosis factor-alpha (TNF-alpha)." (PMID 36235607, 2022). "Studies have reported that many inflammatory cytokines, including interleukin (IL)-1, IL-6, and tumor necrosis factor (TNF)-α, increase during aging and play a vital role in osteoporosis." (PMID 35336732, 2022). "Elevated levels of proinflammatory cytokines such as tumor necrosis factor (TNF), interleukin 1 (IL-1), interleukin 6 (IL-6), or interleukin 17 (IL-17) are also characteristic of osteoporosis." (PMID 35955603, 2022). "In the future, verification of the pharmacological effect of TH in animal models of osteoporosis through administration of inflammatory cytokines and in RANKL + TNF-α-induced cell models will be valuable in understanding the anti-osteoporosis effect of TH." (PMID 36297038, 2022). "During osteoporosis, CD4+CD28- T lymphocytes expressed higher levels of TNF-α and intensely induced the activation of TRAP in osteoclasts as compared with CD4+CD28+ T lymphocytes." (PMID 34341698, 2021). "Moreover, the expression of TNF-α and IL-17A in old rats after long-term drinking was significantly higher than that in the young rats, indicating that the effects of alcohol on the inflammatory response to promote osteoporosis was more significant in the old rats." (PMID 34336709, 2021). "In this study, we tried to evaluate the relationships among 14-3-3η protein, TNF-α, and IL-6, I-CTX and PINP, and analyzed the mechanism of 14-3-3η protein affecting the development of osteoporosis in patients with RA." (PMID 32704255, 2020). "After 3 months of ST treatment, the IL-6 and TNF-α levels of the rats in the OVX+ST group were reduced, and the TGF-β1 content was higher than model rats, indicating that ST can improve osteoporosis, which the effect is slightly lower than ALE." (PMID 32670052, 2020). "The results showed that SNP in TNF-α rs1800629 interacted with rs3782905 in VDR gene on overall and lumbar spine osteoporosis among elderly women." (PMID 31887189, 2019). "The present study aims to evaluate the independent and interactive effects of SNPs in VDR and TNF-α genes on BMD and osteoporosis in elders from the Taichung Community Health Study for Elders (TCHS-E) in Taichung City, Taiwan." (PMID 31887189, 2019). "In this study, we focused on investigating the interaction between SNPs in TNFα and its receptors (TNFRSF1A and TNFRSF1B), MAP infection, and active osteocalcin levels (an osteoporosis marker) in blood samples from RA patients." (PMID 31817071, 2019). "We detected significant interactions between TNF-α SNP rs1800629 and VDR rs3782905 on overall and lumbar spine osteoporosis in women after covariate adjustment and type 1 error correction (all p < 0.05)." (PMID 31887189, 2019).
osteoporosis (continued). "Here, we studied the frequency and effects of SNPs in TNFα/TNFRSF1A/TNFRSF1B in RA including gene expression, MAP infection, and osteoporosis marker levels in blood (54 RA and 48 healthy controls)." (PMID 31817071, 2019). "Generally, a Th1 profile and the hyperproduction of pro-inflammatory cytokines, mainly IL-1, IL-6, IL-17 and tumor necrosis factor (TNF)-α, condition the appearance and progression of both primitive and secondary osteoporosis." (PMID 30846811, 2019). "After multivariable adjustment, significant interactions of TNF-α rs1800629 and VDR rs3782905 were observed on overall and lumbar spine osteoporosis." (PMID 31887189, 2019). "In the current study, we found the interactive effect of SNP in TNF-α rs1800629 with rs3782905 in VDR gene on overall and lumbar spine osteoporosis among elderly women." (PMID 31887189, 2019). "Given that macrophages are important mediators of inflammation and can release abundant inflammatory factors that contribute to osteoporosis, we then established an inflammatory macrophage model by treating RAW264.7 cells with TNF-α for 30 min." (PMID 29619269, 2018). "To address inflammation, as the third aspect of osteoporosis, we investigated the effect of DMA on the TNF-α inhibition of BMP-induced osteogenesis." (PMID 28176838, 2017). "IL-17 induces osteoblast and stromal cell production of IL-6, and TNF, which induce RANKL expression, accelerate osteoclastogenesis and lead to osteoporosis." (PMID 24400116, 2014). "WSP-AbM reduced TNF-α, IL-1β, ICAM-1, iNOS, and COX-2 expressions and osteoporosis by the inhibition of NF-κB activation." (PMID 24348690, 2013). "In conclusion, despite the limitations of this study, it can be concluded that localized stem cell administration can accelerate and enhance osseointegration in osteoporosis conditions through various evaluated markers Osx, osteocalcin, collagen type 1, RUNX2, NFATc1, TNFα, and BIV." (PMID 41585122, 2026). "In this study, TNF-α expression and the concentration of TNF-α in the blood serum were not correlated with bone and anthropometric parameters in individuals with CD and osteopenia/osteoporosis." (PMID 41141340, 2025). "It showed that in patients with CD and osteoporosis (group A) there was no statistically significant relation between Cq values for TNF-α gene and the studied parameters." (PMID 41141340, 2025). "In this study, the downregulation of IL-6, TNF-α, IL-1β, MMP3, MMP9, and caspase-3 by curculigoside aligns with previous findings that these factors mediate osteoblast injury and extracellular matrix degradation in osteoporosis." (PMID 40917365, 2025). "The implication is that targeting TNFα or NF-κB could preserve SMAD signaling, potentially enhancing bone mass and offering therapeutic strategies for bone-related disorders like osteoporosis." (PMID 39868289, 2025). "Intriguingly, there was a higher proportion of TNF-α expression increases in HFD-4W mice than in HFD-16W mice, suggesting that inflammation is likely to be intimately involved in the occurrence and development of osteoporosis in the early phase of T2D." (PMID 40225857, 2025). "In patients with CD without osteoporosis (group B), a statistically significant, strong, positive correlation was observed between Cq values for TNF-α and the following values: BMI, BMD of the FN, BMD of L1-L4, and Z-score of L1-L4." (PMID 41141340, 2025). "In osteoporosis, NLRC3 attenuated TNFα+ Th17 cell accumulation in the bone marrow." (PMID 38436712, 2024). "Osteoporosis leads to a decrease in the secretion of OPG by osteoblasts and an increase in the expression and secretion of RANKL, interleukin 1(IL-1), IL-6, IL-11, and tumor necrosis factor α (TNF-α)." (PMID 38098766, 2023). "In this osteoporosis rat model study, RSV supplementation protected against MTX-induced bone damage by inhibiting osteoclastogenesis (reducing TRAP levels) and lowering proinflammatory cytokines such as TNF, IL1, and IL6." (PMID 37239124, 2023).
osteoporosis (continued). "Raloxifene, often prescribed for osteoporosis, has been observed to activate ERs and the extracellular signal-regulated kinase 1/2 (ERK1/2) signaling pathway in human chondrocytes, preventing tumor necrosis factor alpha (TNFα)-induced caspase-3-dependent apoptosis." (PMID 37024929, 2023). "A study involving 45 postmenopausal women showed that the circulating levels of IL-1β, IL-6, and TNF-α in postmenopausal women with osteoporosis were significantly higher than those without osteoporosis." (PMID 37035758, 2023). "Moreover, expressions of genes involved in osteoclast differentiation, TNF, ACP5, and CTSK, were all increased in the osteoporosis group compared to those in the normal control group." (PMID 37339951, 2023). "In postmenopausal women, estrogen deficiency can cause an increase in various cytokines, such as IL-1, IL-6, and TNFα, which induce an increase in RANKL, thereby stimulating osteoclastogenesis and, therefore, playing a fundamental role in the pathophysiology of osteoporosis." (PMID 36829932, 2023). "WWP1 inhibits the differentiation of mesenchymal stem cells (MSCs) into osteoblasts through ubiquitination and proteasomal degradation of JUNB and the lysosomal degradation of CXCR4 following induction by tumor necrosis factor (TNF), thereby promoting inflammation-mediated osteoporosis." (PMID 38129384, 2023). "Serum levels of TNF-α, IL-6, and IL-17 were higher and levels of IL-4 and IL-10 were lower in RA patients when compared to those without osteoporosis." (PMID 35955873, 2022). "TNFα induces osteocyte apoptosis through NF-kB activation contributing to osteoporosis in postmenopausal women, and it induces osteocyte apoptosis and FGF23 increase in glucocorticoid-induced osteoporosis." (PMID 35216216, 2022). "This means that TNFα combined with HUCWJCs did not have an effective therapeutic effect in the treatment of osteoporosis." (PMID 35936064, 2022). "Recent clinical data has also verified that individuals with osteoporosis have higher level of serum TNF-α, indicating that TNF-α may be a crucial part to improve bone health." (PMID 35707276, 2022). "The findings of this work are important because they also highlight that the beneficial effects of stimulation with PEMF are comparable to those of knockout mice for the TNF-α or IL6 genes, suggesting a role of these two mediators in post-menopausal osteoporosis." (PMID 35336776, 2022). "As DANCR correlated to IL6 and TNFα in patients affected by osteoporosis it was suggested that the long and non-coding RNA-DANCR could be used as a biomarker in osteoporosis." (PMID 34640633, 2021). "Both IL-6 and TNF-α promote bone resorption, and the positive correlation of DANCR with serum levels of IL-6 and TNF-α in osteoporosis patients suggest the involvement of DANCR in the pathology of osteoporosis." (PMID 32992908, 2020). "As IL6 and TNF-α are inflammatory markers involved in osteoclastogenesis, it can be inferred that DANCR could serve as a potential biomarker for osteoporosis." (PMID 32664424, 2020). "The elevated level of pro-inflammatory cytokines, mainly tumor necrosis factor alpha (TNFα), in RA blood has negative effects on osteoclast paracrine stimulation, which leads to bone resorption as seen in osteoporosis." (PMID 31817071, 2019). "However, no prior study has explored the independent and interactive effect of the genetic variation of VDR and TNF-α genes on BMD and osteoporosis." (PMID 31887189, 2019). "Besides, naringin improved random skin flap survival and osteoporosis through promoting angiogenesis by regulating the VEGF/VEGFR signaling pathway and inhibiting inflammation by down-regulation of TNF-α and IL-6." (PMID 30298000, 2018). "The aim of the study is to evaluate the association between proinflammatory markers (interleukin [IL]-1β, IL-6, TNF-α) with bone turnover markers (BTMs) in postmenopausal Saudi women with and without osteoporosis." (PMID 28121926, 2017).
osteoporosis (continued). "The study aims to evaluate the associations between proinflammatory markers (IL-1β, IL-6, and TNF-α) with BTMs in postmenopausal Saudi women with and without osteoporosis." (PMID 28121926, 2017). "From this perspective, as biphasic factors, TNF-α and NF-κB may represent ideal therapeutic targets, and TNF-α and NF-κB inhibitors may represent potential therapeutic agents for the treatment of osteoporosis." (PMID 25816130, 2015). "It suggests that T cells activated by ICIs may increase the expression of the receptor activator of nuclear factor-κB ligand (RANKL) and other cytokines, including tumor necrosis factor (TNF)-α and interleukin (IL)-18, IL-17, and IL-12, potentially leading to the development of osteoporosis." (PMID 40143113, 2025). "However, we believe that since osteoporosis is a chronic systemic disease associated with proinflammatory cytokines, such as IL-6 and tumor necrosis factor (TNF)-alpha, studies with long-term follow-up periods are needed to determine the link between LTL and osteoporosis." (PMID 39074257, 2024). "Furthermore, it has been observed that Th2 dominance is related with senile osteoporosis, implying that Th2-type cytokines such as IL-10, IL-6, IL-5, and IL-4 levels rose while Th1-type cytokines such as IL-2,IFN-γ and TNF-α reduced in patients suffering from senile osteoporosis." (PMID 38461235, 2024). "Recent research has revealed that IGU improves disuse osteoporosis in mice by inhibiting sclerostin and the receptor activator of NF-κB ligand (RANKL) through the extracellular signal-regulated kinase/early growth response protein 1/TNF-α pathway in osteocytes." (PMID 39449973, 2024). "Marrow fat secretes several adipokines, such as Leptin, Adiponectin, TNFα, IL1β, and IL6, which promote chronic inflammatory responses and are shown to be highly correlated with bone cancer metastasis and markers for the progression of bone diseases such as osteoporosis." (PMID 39056808, 2024). "Given the effect of TNF-α on bone resorption and bone destruction, as well as the inflammatory characteristics of NAFLD, we speculate that TNF-α also plays a role in NAFLD-induced osteoporosis." (PMID 36967758, 2023). "Moreover, the decrease in proinflammatory cytokines including TNF-α, IL-6, and G-CSF might be responsible for the protective effect of GNS on osteoporosis." (PMID 37041523, 2023). "Patients with PBC exhibit elevated levels of inflammatory cytokines, including IL-1, IL-6, TNF-α, which can directly or indirectly promote osteoclast formation and activation via the RANKL-RANK signaling pathway, leading to increased bone resorption and osteoporosis." (PMID 38162659, 2023). "There are reports in the literature stating that an increased production of TNF-α, which inhibits the differentiation of osteoblasts and stimulates the production of RANKL, contributes to less bone formation in elderly animals and thus contributes to senile osteoporosis." (PMID 35053012, 2021). "Further experiments showed that Rtn4-Exos attenuated TNF-α-induced cytotoxicity and apoptosis by sponging miR-146a, suggesting that Rtn4-Exos might serve as promising candidates for the treatment of TNF-α-induced osteoporosis." (PMID 32400849, 2020). "It was also previously suggested that F. deltoidea extract has potent inflammation inhibitory properties that significantly downregulate the expression of bone inflammatory cytokines such as NF-κβ, TNF-α, and IL-6 to normal levels, as opposed to their excessive increase in osteoporosis." (PMID 33456747, 2020). "The TNF-α gene may have joint and interactive effects with LEPR in osteoporosis development." (PMID 31887189, 2019). "In this study, we examined the interaction between VDR gene and TNF-α gene on osteoporosis in Chinese elders in Taiwan to determine whether or not VDR gene is associated with the regulation of immune functions." (PMID 31887189, 2019).
osteoporosis (continued). "A previous study reported that a high TNF-α level was observed in osteoporosis patients with maintenance hemodialysis of chronic renal failure for more than 33 months compared with those without osteoporosis." (PMID 31887189, 2019). "The tumor necrosis factor (TNF) superfamily, composed of both ligands and receptors, is one of the most successfully and frequently targeted protein families with clinical relevance to diverse diseases as cancer, autoimmunity, infections, graft rejection, inflammation and osteoporosis." (PMID 26266038, 2015). "The results of KEGG and GO functional enrichment suggest that curculigoside may treat osteoporosis by inhibiting the overproduction of osteoclastic cytokines and their induction of oxidative damage, primarily through modulation of the Rap1, IL-17, HIF-1, and TNF signaling pathways." (PMID 40917365, 2025). "In patients with celiac disease and osteopenia/osteoporosis (group A), the lack of correlation between TNF-α expression and the parameters under study may reflect advanced bone metabolism disorders with a complex, multifactorial basis, wherein potentially other factors may mask the effects of TNF-α." (PMID 41141340, 2025). "Osteoporosis in LCH, particularly in young adults, is uncommon and may result from altered bone remodeling because of Langerhans cell infiltration, which stimulates osteoclast activity via inflammatory cytokines such as IL-1, TNF-α, and RANKL, leading to bone resorption." (PMID 40979825, 2025). "This study showed that eosinophils in patients with COPD could be activated by TNF-α, suggesting its pro-inflammatory roles in eosinophil activation in COPD in addition to IFN-γ, contributing to the pathogenesis of COPD comorbidities such as osteoporosis and cardiovascular disease." (PMID 39439801, 2024). "Hence, our findings suggested that Rtn4-Exos attenuated TNF-α-induced cytotoxicity and apoptosis in murine MC3T3-E1 cells by sponging miR-146a, suggesting that Rtn4-Exos may serve as novel candidates for treating osteoporosis." (PMID 32400849, 2020). "Our results showed that exosomes derived from circ-Rtn4-modified BMSCs (Rtn4-Exos) inhibited TNF-α-induced cytotoxicity and apoptosis in murine MC3T3-E1 cells via regulating miR-146a expression, thus indicating that Rtn4-Exos may serve as novel agents for the treatment of osteoporosis." (PMID 32400849, 2020). "Tumor necrosis factor-α (TNF-α) is a well-recognized inhibitory factor in BMSC osteogenic differentiation and was shown to induce miR-23b expression, which could lower Runt-related transcription factor 2 (Runx2) and consequently reduce osteogenesis leading to severe osteoporosis in mice." (PMID 32846921, 2020). "We found that the odds of overall osteoporosis among elderly women carrying CG/CC genotype of VDR rs3782905 were significantly higher than those among carrying TNF-α rs1800629 GG genotype (adjusted OR: 3.66 [95% CI: 1.62–8.26] but not among those carrying TNF-α rs1800629 AG/AA genotype." (PMID 31887189, 2019). "Thus, CHIP targets Osx for ubiquitination and degradation in osteoblasts after chronic exposure to TNF-α, and inhibition of CHIP expression in osteoblasts may be a new mechanism to limit inflammation-mediated osteoporosis by promoting their differentiation into osteoblasts." (PMID 25818514, 2015). "In this study, TNF-α, both in terms of gene expression and serum level, does not appear to correlate with BMD status in individuals with CD and osteopenia/osteoporosis." (PMID 41141340, 2025). "Interestingly, the proportion of increased TNF-α expression was higher in HFD-4W mice than in HFD-16W mice, indicating that inflammation may play an early important role in the development of T2D-induced osteoporosis, consistent with our transcriptomic analysis." (PMID 40225857, 2025).